ANO10 (anoctamin 10)
Description:
Does not exhibit calcium-activated chloride channel (CaCC) activity. Can inhibit the activity of ANO1.
Synonyms: TMEM16K; FLJ10375; MGC47890; SCAR10
Tractability: Small molecule: a structure with a bound ligand is known. Antibody: UniProt places it where antibodies can reach, with high confidence; its Gene Ontology location is reachable by antibodies, with high confidence; UniProt predicts a signal peptide or a membrane-spanning region; the Human Protein Atlas places it where antibodies can reach. PROTAC: ubiquitination databases record sites on it; its protein half-life has been measured.
Gene: Protein-coding gene on chromosome 3 (43,354,859 to 43,691,594, reverse strand). Ensembl gene ENSG00000160746.
Subcellular location: Cell membrane
Subcellular location (Human Protein Atlas): Plasma membrane; Primary cilium; Vesicles
Pathways (Reactome):
Disease: Induction of Cell-Cell Fusion
Transport of small molecules: Stimuli-sensing channels
Gene Ontology:
Molecular function: calcium-activated cation channel activity; intracellularly calcium-gated chloride channel activity; chloride channel activity
Biological process: chloride transmembrane transport; monoatomic ion transmembrane transport; monoatomic cation transmembrane transport
Cellular component: membrane; plasma membrane
Genetic constraint (gnomAD): Loss-of-function variants: 74 observed, 72.39 expected, observed/expected ratio (o/e) 1.02, 90% interval 0.85 to 1.24. The upper end of that interval is the gene's LOEUF score, 1.24, which puts it in group 5 of 6, group 1 being the genes least tolerant of losing a copy. Missense variants: 711 observed, 788.11 expected, observed/expected ratio (o/e) 0.9, 90% interval 0.85 to 0.96. Synonymous variants: 277 observed, 290.93 expected, observed/expected ratio (o/e) 0.95, 90% interval 0.86 to 1.05.
Gene-disease validity (ClinGen):
ClinGen rates the evidence that ANO10 causes each of these diseases.
autosomal recessive spinocerebellar ataxia 10 (autosomal recessive): Definitive.
Homologues: Orthologues: chimpanzee ANO10 (99% identical), macaque ANO10 (98% identical), pig ANO10 (94% identical), mouse Ano10 (92% identical), rat Ano10 (91% identical), guinea pig ANO10 (86% identical), tropical clawed frog ano10 (69% identical), zebrafish ano10a (65% identical). Paralogues in human: ANO8 (29% identical), ANO4 (29% identical), ANO3 (27% identical), ANO7 (27% identical), ANO6 (27% identical), ANO5 (27% identical), ANO2 (25% identical), ANO1 (24% identical), ANO9 (21% identical), PPP1R7 (10% identical).
Diseases named in the same sentence as ANO10 in open-access papers:
ANO10 is named in the same sentence as 34 diseases in open-access papers, as found by Europe PMC text mining. Sharing a sentence is not in itself a finding about the gene and the disease. The quoted sentences say what the papers report.
Ataxia (14 papers, 2014 to 2024). Ataxia refers to impaired coordination of voluntary muscle movement. "Considering ANO10’s scrambling activity and that variants in ANO10 lead to SCAR10, abnormal lipid distribution in ER and other membranes was proposed as a potential cause of ataxia." (PMID 35648332, 2023). "Because 2 out of 40 patients (5 %) from our cohort carried mutations in ANO10, we suggest that defects in this gene should be considered in patients with unexplained ataxia and low CoQ10 in skeletal muscle." (PMID 25182700, 2014). "In our genetic characterization of a group of patients with unexplained recessive or sporadic cerebellar ataxia and low muscle CoQ10, we identified pathogenic mutations in ANO10 in two families." (PMID 25182700, 2014). "Furthermore, ANO10 variants (c.132dupA [p.Asp45fs] and c.1244C>G [p.Ser415*]) were found to be the underlying cause of ataxia in two Korean siblings." (PMID 35648332, 2023). "Cerebellar ataxia associated with ANO10 mutation (ARCA3) presents a disabling cerebellar syndrome." (PMID 28316589, 2017). "It has been postulated that cerebellar ataxia in patients with ANO10 deficiency may be due to abnormal calcium signaling in Purkinje cells." (PMID 25182700, 2014). "Homozygous or compound heterozygous ANO10 variants are considered causative factors for SCAR10, a rare, gradually progressive spinocerebellar ataxia." (PMID 35648332, 2023). "Dysregulation of calcium signalling in Purkinje cells due to ANO10 defects is proposed as the main mechanism leading to spinocerebellar ataxia autosomal recessive type 10 (SCAR10), a rare, slowly progressive spinocerebellar ataxia." (PMID 35648332, 2023). "Our results highlight this as SPG7 was not covered by one ataxia panel, SYNE1 by another, and ANO10 was not included in either panel." (PMID 25976027, 2015).
autosomal recessive cerebellar ataxia (3 papers, 2014 to 2023). "Mutations in ANO10 has been associated with autosomal recessive cerebellar ataxia in only five families." (PMID 25182700, 2014). "Anoctamin-10 function has been associated with autosomal recessive cerebellar ataxia." (PMID 35207044, 2022).
prostate carcinoma (3 papers, 2020 to 2024). A carcinoma that arises from epithelial cells of the prostate gland. "According to these results, we hypothesized that lower ANO5 and higher ANO10 expression would correlate with worse outcomes in prostate cancer." (PMID 32027096, 2020). "One of the key observations made in our analysis was much lower expression of ANO1, ANO8 and ANO10 in LNCap low-metastatic and DU145 moderately-metastatic cells when compared to PC3 highly-metastatic prostate cancer cells." (PMID 38773164, 2024). "Also, considering that DNA methylation mainly affects gene expression at the level of transcription, it was reasonable to speculate that transcription is the primary process through which the expression of ANO1, ANO8, and ANO10 is regulated in LNCaP, DU145, and PC3 prostate cancers." (PMID 38773164, 2024).
autosomal recessive spinocerebellar ataxia (2 papers, 2014 to 2023). "Along with ANO5, which has been connected to specific types of muscular dystrophy, ANO6 and ANO10 have also been linked to Scott syndrome and autosomal recessive spinocerebellar ataxia, respectively." (PMID 36836529, 2023).
coenzyme Q10 deficiency (2 papers, 2014 to 2024). A genetically heterogeneous condition, typically inherited in an autosomal recessive fashion, characterized by coenzyme Q10 deficiency. "The detection of pathogenic ANO10 mutations in our patient with the ataxic form of CoQ10 deficiency prompted us to perform sequencing of ANO10 in 36 further patients with low CoQ10 in muscle, fibroblasts, or CSF, and we detected pathogenic mutations in one additional patient." (PMID 25182700, 2014).
Cognitive impairment (2 papers, 2022 to 2023). Abnormal cognition is characterized by deficits in thinking, reasoning, or remembering. "Though rarely found in a homozygous state, ANO10 c.132dupA is associated with cognitive impairment, ranging from mild to severe." (PMID 35648332, 2023).
neuropathy (2 papers, 2022 to 2023). A disorder affecting the nervous system that manifests with pain, tingling, numbness, and/or muscle weakness. "The absence of neuropathy from patients with ANO10 pathogenic variants led to the additional nomenclature of the SCAR10 disease as ARCA3, and its categorization in the group of ARCAs without neuropathy alongside ARCA1 and ARCA2." (PMID 35648332, 2023).
hepatocellular carcinoma (1 paper, 2023). A malignant tumor that arises from hepatocytes. "ANO10 upregulation in hepatocellular carcinoma, and association with poor prognosis, further suggest an involvement in the immune defence." (PMID 35648332, 2023).
tumor (2 papers, 2022 to 2023). "ANO10 presumably regulates the immune microenvironment of the tumour." (PMID 35648332, 2023). "The genes with low expression in the tumor group were CRISP3, FAM3D, SCNN1B, CRISP2, RBM20, PHYHIP, C2orf54, SLC5A1, PTCRA, C15orf59, and ANO10." (PMID 35389773, 2022).
ANO10 also shares sentences with these, for which no sentence is quoted: cerebellar ataxia (3 papers); ataxia telangiectasia (2); neurological disorder (2); Scott syndrome (2); spastic ataxia (2); Ataxia with vitamin E deficiency (1); autonomic dysfunction (1); bone osteosarcoma (1); brain malformations (1); Cerebellar atrophy (1); Dystonia (1); episodic ataxia (1); genetic diseases (1); gnathodiaphyseal dysplasia (1); hereditary spastic paraplegia (1); Intellectual disability (1); Limb tremor (1); limb-girdle muscular dystrophy (1); lung carcinoma (1); movement disorder (1); multisystem atrophy (1); muscular dystrophy (1); Obesity (1); Spastic paraparesis (1); Spasticity (1).